APP (amyloid beta precursor protein)
Diseases named in the same sentence as APP in open-access papers (continued):
Sharing a sentence is not in itself a finding about the gene and the disease.
Alzheimer disease (continued). "In APP/PS1 transgenic mice as a model of Alzheimer’s disease, lotus seedpod PACs administered for 5 months improved cognitive dysfunction and long-term potentiation through the stimulation of the CREB–BDNF pathway." (PMID 41221046, 2025). "Individuals with Down syndrome have a greatly increased risk of Alzheimer’s disease (DSAD), due to the presence of the APP gene on chromosome 21 that encodes the amyloid-β precursor protein (APP)." (PMID 39841661, 2025). "APP (Amyloid Precursor Protein) is a transmembrane glycoprotein best known for its role in Alzheimer’s disease, but it also regulates cell growth, survival, and adhesion." (PMID 40881172, 2025). "Alzheimer's disease (AD) is a progressive neurodegenerative disorder with perturbations in the amyloid precursor protein (APP)." (PMID 39668579, 2025). "In rodent models of Alzheimer’s disease (e.g., APP/PS1 and 5xFAD), butyrate administration has been shown to reverse Aβ-induced cognitive impairment by restoring hippocampal BDNF expression and activating downstream CREB/TrkB signaling pathways." (PMID 41299728, 2025). "Understanding ONOO− reduction by the E2 domain of APP expands our knowledge of copper proteins in mitigating oxidative stress and elucidates their physiological and pathological roles, particularly in Alzheimer's disease." (PMID 39670805, 2025). "These include Aβ and APP C-terminal fragments in Alzheimer’s disease, altered α-synuclein in Parkinson’s disease, abnormal huntingtin protein in Huntington’s disease, and defective SOD1 and TDP-43 in ALS." (PMID 40799366, 2025). "The brain-enriched adaptor protein FE65 has been shown to interact with Alzheimer’s disease amyloid precursor protein (APP) to alter the processing of APP." (PMID 39857327, 2025). "For instance, CRISPRi has been employed to knock down the expression of amyloid precursor protein (APP), a key factor in Alzheimer’s disease pathology." (PMID 40869897, 2025). "This approach is informed by evidence linking APP alternative splicing to Alzheimer’s disease (Sandbrink, Masters, and Beyreuther 1996; Love, Hayden, and Rohn 2015)." (PMID 40855644, 2025). "In humans, circAβ-a from the APP gene translates into an Aβ-containing peptide that aggregates and drives amyloid-β (Aβ) deposition, providing an alternative pathway for Alzheimer’s disease (AD) pathogenesis." (PMID 41384038, 2025). "Accordingly, IRE-modulated APP expression in Alzheimer’s disease has great therapeutic potential through targeting mRNA structures." (PMID 40438504, 2025). "Given APP’s central role in Alzheimer’s disease, examining its RNA isoforms is critical; changes in their expression or structure can influence the production and processing of the amyloid precursor protein and, consequently, amyloid plaque formation." (PMID 40177266, 2025). "For example, the amyloid precursor protein (APP) gene knock-in rat model for Alzheimer’s disease exhibits pathologies and disease progression resembling more closely to the human condition compared to transgenic mice overexpressing the APP gene." (PMID 40013092, 2025). "The amyloid precursor protein (APP) family is ubiquitously expressed in the mammalian brain and implicated in Alzheimer’s disease." (PMID 40512617, 2025). "The amyloidogenic processing of amyloid precursor protein (APP) plays a pivotal role in the pathogenesis of Alzheimer’s disease (AD), primarily through the generation of amyloid-beta (Aβ) peptides, which aggregate to form toxic plaques in the brain." (PMID 40722590, 2025). "A. butyriciproducens was reported to improve cognitive impairment in LPS-induced and APP/PS1 mouse models of Alzheimer’s disease." (PMID 40963595, 2025). "People with Down syndrome (DS) are disproportionately affected by Alzheimer's disease (AD), due to triplication of chromosome 21, which contains the amyloid precursor protein (APP) gene." (PMID 40673442, 2025).
Alzheimer disease (continued). "While APP is best known for its central role in Alzheimer’s disease pathogenesis, its physiological functions remain incompletely understood." (PMID 41284713, 2025). "The aerobic exercise increased levels of CYP46A1 as well as its metabolite 24-hydroxycholesterol in an APP/PS1 mouse model of Alzheimer’s disease." (PMID 41462691, 2025). "In the APP/PS1 mouse model of Alzheimer’s disease, lifelong choline supplementation reduced the amyloid-β plaque, microglia activation, and improved the spatial memory deficits." (PMID 40806292, 2025). "In 5xFAD mice and other transgenic models of Alzheimer’s disease, overexpression of APP is accompanied by physiological and structural changes in the hippocampus, leading to the deterioration of cognitive abilities and decreased synaptic integrity." (PMID 40321747, 2025). "In two different transgenic mouse models of Alzheimer’s disease, APP/PS1 and 5xFAD, compound 79 significantly reduced both total Aβ and pyriform Aβ concentrations in the brain and restored cognitive function." (PMID 41103911, 2025). "Amyloid precursor protein (APP)-derived amyloid-β (Aβ) peptides form pathological aggregates in Alzheimer’s disease (AD)." (PMID 40676215, 2025). "This schematic illustration summarizes the effects of calcium alpha‐ketoglutarate (CaAKG) on synaptic plasticity in a mouse model of Alzheimer's disease (APP/PS1)." (PMID 40959937, 2025). "Under APP/PS1 transgenic mice (the most popular Alzheimer’s disease model), the treatment with VB drastically inhibited the activation of microglia and astrocytes." (PMID 41393957, 2025). "Researchers utilized Amyloid Precursor Protein/Presenilin-1 (APP/PS1) transgenic mice as models for Alzheimer’s disease." (PMID 40098612, 2025). "IRE-containing mRNAs have been found in a variety of other proteins recently, including APP in Alzheimer’s disease, α-synuclein in Parkinson’s disease, and the α-hemoglobin stabilizing protein." (PMID 40508094, 2025). "APP/PS1 mice with Alzheimer’s disease trained in a water maze at 3 months of age and tested at 7 months showed worse memory than wild-type animals." (PMID 40822853, 2025). "Due to the trisomy of chromosome 21, which harbours the gene encoding for the amyloid precursor protein (APP), people with Down syndrome progressively develop Alzheimer’s disease neuropathology starting early in life." (PMID 39853302, 2025). "By contrast, aberrantly processed, secreted amyloid-β (Aβ) peptides derived from amyloid precursor protein (APP) form pathological extracellular amyloidogenic aggregations in late-stage Alzheimer’s disease (AD)." (PMID 40676215, 2025). "This leads to the overexpression of APP, increasing the production and aggregation of amyloid‐beta (Aβ) peptides, which are crucial in the pathogenesis of Alzheimer's disease." (PMID 39757377, 2025). "We investigated mutations linked to early-onset Alzheimer’s disease (EOAD), particularly in the APP, PSEN1, and PSEN2 genes, which affect amyloid-beta production and neuronal integrity." (PMID 40725212, 2025). "For instance, our research has shown that AEP cleaves APP and tau, which accelerates Alzheimer’s Disease pathology." (PMID 40371638, 2025). "Our findings enhance the understanding of ONOO− reduction by the E2 domain of APP, expand our knowledge of copper proteins in mitigating oxidative stress, and elucidate their physiological and pathological roles, particularly in Alzheimer's disease." (PMID 39670805, 2025). "In turn, APP, widely recognized as a key molecular player in Alzheimer’s disease pathogenesis, is also a critical factor in various physiological processes, ranging from cellular differentiation to complex cascades determining cell fate." (PMID 41465271, 2025). "Further, anthocyanin-enriched bilberry fractions were discovered to alter APP processing in a mouse model of Alzheimer’s disease." (PMID 40807615, 2025).
Alzheimer disease (continued). "Amyloid precursor protein (APP) is a type-I membrane-spanning protein, which plays a central role in Alzheimer’s disease (AD) pathology." (PMID 40859033, 2025). "AVE0991 treatment in the APP/PS1 double-transgenic mouse model of Alzheimer’s disease suppressed astrocyte-mediated inflammation by downregulating the expression profile of IL-1β, IL-6, and TNF-α in the brain cortex." (PMID 40565247, 2025). "The regulation of amyloidogenic APP processing is a complex interplay of enzymes, proteins, and signaling pathways, all of which contribute to the development and progression of Alzheimer’s disease." (PMID 40722590, 2025). "BHB crossed the blood–brain barrier and rescued memory, improved cognitive function, and increased neuronal plasticity in two different mouse models of Alzheimer’s disease (PS1/APP and 5XFAD)." (PMID 40800722, 2025). "Familial Alzheimer’s disease (fAD) is a rare, inherited, autosomal dominant form of AD caused by mutations in PSEN1, PSEN2 and APP." (PMID 40542358, 2025). "Common transgenic rat models, similar to mouse models, utilize APP and PSEN1 transgenes containing mutations representative of inherited Alzheimer’s disease." (PMID 40426657, 2025). "When combined, iron can influence the development of Alzheimer’s disease by controlling the levels of APP, amyloid-β, and tau protein hyperphosphorylation." (PMID 40438504, 2025). "For example, patients with dementia carrying P/LP Variants in genes such as APP, PSEN1, and PSEN2 exhibit distinct prognoses compared to those with sporadic Alzheimer’s disease." (PMID 40427062, 2025). "Dysregulation of membrane trafficking is observed in Alzheimer’s disease and includes defects in the trafficking of both APP and the secretases which result in elevated levels of APP processing and amyloid-β production." (PMID 40302938, 2025). "Therefore, mutations in APP and/or enzyme responsible for APP processing are associated with changes in the level and identity of the amyloid-β products, which may be an important factor in the early onset of Alzheimer’s disease." (PMID 40302938, 2025). "This study investigates the effects of AE on Alzheimer's disease (ad) using an ad model with APP/PS1 transgenic mice and validation experiments in HT22 cells." (PMID 40125832, 2025). "In Alzheimer’s disease (AD), impaired lipid metabolism contributes to Aβ aggregation and tau pathology, with cholesterol modulating APP processing and ApoE4 impairing Aβ clearance." (PMID 40880849, 2025). "Oxidation of a single methionine residue at position 35 of the Aβ was observed in the genetic APP model of Alzheimer’s disease in mice." (PMID 40563328, 2025). "While most Alzheimer’s disease cases are sporadic, FAD mutations in PSEN1, PSEN2, and APP are nearly completely penetrant." (PMID 39754192, 2025). "Alzheimer’s disease (AD) pathogenesis is correlated with the membrane content of various lipid species, including cholesterol, whose interactions with amyloid precursor protein (APP) have been extensively explored." (PMID 39859269, 2025). "To address this question, we utilized an AAV‐vector‐mediated approach to express Ctsb in skeletal muscle of APP/PS1 Alzheimer's disease (AD) model mice." (PMID 41047763, 2025). "The amyloid precursor protein (APP) has been extensively studied in the context of Alzheimer's disease (AD) due to its role in generating amyloid plaques, which represents a hallmark of AD pathology." (PMID 40739894, 2025). "Recently, we observed that crossbreeding FAM19A5-LacZ KI mice with APP/PS1 mice, a mouse model of Alzheimer’s disease (AD), extended the lifespan of APP/PS1 mice." (PMID 40763294, 2025). "Amyloid beta (Aβ) is an aggregation-prone peptide that accumulates in the Alzheimer’s disease (AD) brain and is generated through proteolytic cleavage of the Amyloid Precursor Protein (APP)." (PMID 40693240, 2025).
Alzheimer disease (continued). "The overexpression of amyloid-β precursor protein (APP) in the brain of Alzheimer’s disease (AD) leads to the binding of APP to Fe65 protein, which, in turn, triggers the secretion of amyloid-β, leading to the pathogenesis of AD." (PMID 40141135, 2025). "Mutations in the genes encoding APP, Presenilin-1 (PSEN1), and PSEN2 result in early-onset Alzheimer’s disease (AD)." (PMID 40783385, 2025). "Posttranslational modification (PTM) of the amyloid precursor protein (APP) plays a critical role in Alzheimer’s disease (AD)." (PMID 39744941, 2025). "In an Alzheimer’s disease (AD) model, folic acid protected neuronal cells from DNA methylation alterations of the APP and PS1 genes by amyloid β oligomers and attenuated neuronal toxicity." (PMID 40724917, 2025). "Well-known mutations in APP, PSEN1, and PSEN2 genes are primary causes of autosomal dominant early-onset Alzheimer’s disease (EOAD)." (PMID 41465142, 2025). "We provide comprehensive preclinical evidence supporting the therapeutic potential of the traditional Chinese medicine (TCM)-derived formulation NeuproGemp in attenuating Alzheimer’s disease (AD)-like phenotypes in the APP/PS1 transgenic mouse model." (PMID 41194875, 2025). "Aberrant DNA methylation has been observed in genes linked to neurodegeneration, including APP, PSEN1, and TREM2 in Alzheimer’s disease (AD), as well as SNCA and LRRK2 in Parkinson’s disease (PD)." (PMID 40076852, 2025). "This review examines a small interfering RNA (siRNA) designed for intrathecal (IT) injection, which reduces the formation of amyloid beta precursor protein (APP), a critical factor in the pathology of Alzheimer's disease (AD)." (PMID 41599628, 2025). "β-secretase 1 (BACE1) has been shown to contribute to Alzheimer’s disease (AD) through its cleavage on amyloid precursor protein (APP)." (PMID 40507910, 2025). "Amyloid precursor protein (APP), more renowned for its involvement in Alzheimer’s disease (AD), is the precursor of the amyloid-beta (Aβ) peptide, which is believed to be heavily implicated and a cause of neurotoxicity in AD pathogenesis." (PMID 41614805, 2025). "The triplication of the amyloid precursor protein (APP) gene, located on chromosome 21, is sufficient to cause early-onset Alzheimer’s disease (AD), making DS the most prevalent genetically determined form of the condition." (PMID 41213934, 2025). "In this study, we explored the therapeutic potential of PF-04691502, a dual PI3K/mTOR inhibitor, in Alzheimer’s disease (AD)-like pathology using male and female B6.Cg-Tg(APPswe, PSEN1dE9)85Dbo/Mmjax mice (APP/PS1), a well-established transgenic model of AD." (PMID 41002439, 2025). "Presenilin 1 (PSEN1) and amyloid precursor protein (APP) are well-established genetic factors associated with early-onset familial Alzheimer’s disease (EOFAD), whereas apolipoprotein E4 (APOE4) is a recognized genetic risk factor for sporadic late-onset Alzheimer’s disease (LOAD)." (PMID 40244244, 2025). "ADAM10 cleaves amyloid precursor protein (APP) to contribute to the pathophysiology of Alzheimer’s disease." (PMID 39211038, 2024). "Masitinib is a multi-kinase inhibitor that also inhibits fibroblast growth factor receptors and has been identified as a synaptoprotective agent in a dual amyloid precursor protein (APP)/presenilin 1 (PSEN1) mouse model of Alzheimer’s disease (AD)." (PMID 39598703, 2024). "Oleuropein enhances the non-amyloidogenic pathway by facilitating amyloid precursor protein (APP) clearance, inhibiting amyloid-beta (Aβ) aggregation, and disrupting preformed Aβ fibrils, positioning it as a promising therapeutic agent for Alzheimer’s disease." (PMID 39585054, 2024). "Diving deeper into to the evidence chains, Sulindac, an inhibitor of PTGS1 and PTGS2, has been predicted as a potential therapy for FXS by linking these two proteins to their involvement in Alzheimer’s disease and amyloid precursor protein (APP) processing." (PMID 38977662, 2024).
Alzheimer disease (continued). "For example, significant reductions in [11C]UCB-J and [18F]SDM-16 SUVR were detected in the hippocampus of the APP/PS1 mouse model of Alzheimer’s dementia (AD), in which an independent ultramicroscopy study showed significant hippocampal synaptic degeneration." (PMID 39134769, 2024). "For case study, the LCM is used to target the amyloid beta precursor protein, a known drug target for Alzheimer’s disease." (PMID 38647700, 2024). "Metformin promotes CMA: this action decreases amyloid β deposition in the brain of amyloid precursor protein (APP)/presenilin 1 (PS1) mouse model of Alzheimer’s disease." (PMID 39201569, 2024). "It is well-established that aberrant splicing and metabolism of the APP, leading to the production of beta-amyloid, constitutes the critical pathological basis for Alzheimer’s disease." (PMID 38874508, 2024). "JWX-A0108 improved the learning and memory function of Alzheimer’s disease model APP/PS1 mice by decreasing the expression of TNFalpha, IL-1beta, and IL-6 and also decreasing the phosphorylation of NF-kappaB." (PMID 37994990, 2024). "These complexes synchronize Alzheimer’s disease-related genes, including APP, glycogen synthase kinase 3 beta, β-site of APP cleaving enzyme 1, and neprilysin." (PMID 39000382, 2024). "Study about loss of HRD1-mediated protein degradation have shown that the protein levels of HRD1 are significantly decreased in the cerebral cortex of Alzheimer’s disease patients, leading to the accumulation of APP." (PMID 39301473, 2024). "For instance, in Alzheimer’s disease miR-143-3p inhibits amyloid precursor protein (APP) phosphorylation and beta-amyloid (Aβ) generation by targeting death-associated protein kinase 1 (DAPK1)." (PMID 39402582, 2024). "Another protein actively involved in TBI is the amyloid-beta precursor protein (APP), widely known in the context of Alzheimer’s disease pathogenesis." (PMID 39595962, 2024). "In the CNS, amphisomes are required for the degradation of C99B, C83, and amyloid precursor protein (APP), proteins whose accumulation is seen in Alzheimer’s Disease (AD)." (PMID 38534758, 2024). "In Alzheimer’s disease, ROS stimulate the cleavage of amyloid precursor protein (APP), enhancing the production of Aβ peptides which aggregates to form toxic Aβ plaques." (PMID 39204080, 2024). "On the other hand, in another study, it has been found that SORL1 collaborates with APP, influencing transportation and proteolysis pathways, thereby contributing to the advancement of Alzheimer's disease." (PMID 38577023, 2024). "This is particularly evident in the Alzheimer’s disease pathway, where key genes involved in amyloid processing and tau protein pathology, such as APP and MAPT, exhibit significant increases in expression." (PMID 38927081, 2024). "Hong H., Li Y., Su B. Identification of circulating miR-125b as a potentialbiomarker of Alzheimer’s disease in APP/PS1 transgenicmouse." (PMID 38680184, 2024). "In a model of Alzheimer’s disease, it has been demonstrated that the cleavage and degradation of APP are regulated by JNK." (PMID 38304741, 2024). "In GOA, Alzheimer’s disease has been linked to plasma lipoprotein assemblies, reverse cholesterol transport (RCT), catabolic processing of amyloid precursor protein (APP), and activation of the immune response." (PMID 38542318, 2024). "To strengthen the specificity of FOXO1-mediated effects, we have made the comparative analysis using the APPswe/PS1dE9 (APP/PS1) mouse model of Alzheimer’s disease." (PMID 38556884, 2024). "Studies have also shown that an increase in BDNF levels in Alzheimer’s disease leads to a reduction in the production of toxic Aβ through alpha-secretase processing of APP, as well as inhibition of tau phosphorylation." (PMID 39596443, 2024). "BACE2, along with BACE1, has been extensively studied in the context of Alzheimer’s disease, as both enzymes are responsible for processing APP into neurotoxic Aβ peptides." (PMID 39109301, 2024).